MTNR1B (melatonin receptor 1B)
Diseases named in the same sentence as MTNR1B in open-access papers (continued):
Sharing a sentence is not in itself a finding about the gene and the disease.
Stroke (2 papers, 2022 to 2024). Sudden impairment of blood flow to a part of the brain due to occlusion or rupture of an artery to the brain. "MTNR1B rs10830963 polymorphism modified the association between night shift work and incident stroke (Pfor interaction =0.010)." (PMID 35411403, 2022). "A significant interaction was found between MTNR1B rs10830963 polymorphism and night shift work on the risk of developing stroke in the multivariable Cox model (Pfor interaction=0.010)." (PMID 35411403, 2022). "Cox regression analyses of MTNR1B rs10830963 variants and night shift work on incident stroke among employed participants in the UK Biobank." (PMID 35411403, 2022). "Association of night shift work with incident stroke stratified by MTNR1B rs10830963 polymorphism among employed participants in the UK Biobank." (PMID 35411403, 2022). "When stratified by MTNR1B rs10830963 genotypes, night shift work increased the risk of incident stroke only among those with MTNR1B rs10830963 CC (HR 1.23, 95% CI 1.05–1.44) but not GC/GG genotype (model 2)." (PMID 35411403, 2022). "In summary, the risk of night shift work on incident stroke was potentially modified by MTNR1B rs10830963." (PMID 35411403, 2022). "To date, there have been rare studies about the association of MTNR1B rs10830963 polymorphism with incident stroke." (PMID 35411403, 2022). "Cox proportional hazards models were employed to examine the associations of night shift work and MTNR1B rs10830963 with the risk of incident stroke." (PMID 35411403, 2022). "In this case, the associations of night shift work, MTNR1B rs10830963 polymorphism, and incident stroke may be undervalued, namely, the results may be towards null." (PMID 35411403, 2022). "The aim of this study was to investigate whether melatonin receptor type 1B (MTNR1B) rs10830963 polymorphism interacts with night shift work on the risk of incident stroke." (PMID 35411403, 2022). "Taken together, it is reasonable to argue that MTNR1B rs10830963 polymorphism may interact with night shift work to affect the incidence of stroke." (PMID 35411403, 2022). "Particularly, night shift work was most risky to predispose to stroke occurrence among the CC genotype carriers in MTNR1B rs10830963; while among the night shift workers, the G allele seemed to be a protective allele against the detrimental effects of night shift work on incident stroke." (PMID 35411403, 2022). "In addition, due to the modifiable effects of MTNR1B rs10830963, melatonin supplementation may serve as a potential strategy to reduce stroke risk, particularly for the MTNR1B rs10830963 CC genotype carriers when night shifts are inevitably involved." (PMID 35411403, 2022). "Thus, the present study aimed to explore whether MTNR1B rs10830963 polymorphism interacted with night shift work to modify the risk of incident stroke in a population-based cohort study using the UK Biobank." (PMID 35411403, 2022). "More importantly, we found that MTNR1B rs10830963 modified the risks of night shift work on incident stroke." (PMID 35411403, 2022). "Several lines of mechanisms may explain the modification effect of MTNR1B rs10830963 on stroke occurrence." (PMID 35411403, 2022). "In addition, our study found that the interaction of night shift work, MTNR1B rs10830963, with incident stroke, slightly attenuated after adjusting for lifestyle factors." (PMID 35411403, 2022). "There was no statistical significance between stroke characteristics and telomere length, NR3C1, TNF-α, BDNF, MTNR1A, or MTNR1B expression." (PMID 38802847, 2024).
Abdominal obesity (1 paper, 2015). Excessive fat around the stomach and abdomen. "The reported T2D risk alleles of three SNPs, including the T allele of rs243021 near BCL11A, the G allele of the intronic rs10830963 in MTNR1B, and the C allele of the intronic rs2237895 in KCNQ1, contributed to a decreased risk for abdominal obesity in T2D patients." (PMID 26599349, 2015).
Arthritis (1 paper, 2019). Inflammation of a joint. "Case-only analysis indicated that AA genotype frequency in rs2165667 (MTNR1a) AA genotype and rs1562444 (MTNR1b) A/G allele frequency were at increased risk for arthritis and rs10830962 (MTNR1b) CC/CG genotype was at decreased risk for malar rash." (PMID 31815152, 2019). "In MTNR1a/b genes, a significantly increased AA genotype frequency of rs2165667 (MTNR1a) and A allele frequency of rs1562444 (MTNR1b) were found in patients with arthritis than those without (both P = 0.024)." (PMID 31815152, 2019).
autistic disorder (1 paper, 2010). "Interestingly, of the patients carrying variants that were not present in the unaffected group, only those with the splice site mutation in ASMT, and the non-synonymous V124I in MTNR1B met the diagnostic criteria for autistic disorder." (PMID 20377855, 2010). "The promoter variant in MTNR1A was identified in a patient with PDD-NOS and the two MTNR1B mutations were identified in one patient with PDD-NOS (c.-39GC>AA) and one patient with autistic disorder (V124I)." (PMID 20377855, 2010).
cerebrovascular disease (1 paper, 2022).
chordoma (1 paper, 2022). Chordomas are rare malignant tumors arising from embryonic remnants of the notochord in axial skeleton. "Interestingly, our previous study showed that MTNR1B can also interact with Gαi2 in the chordoma cell lines, U-CH1 and MUG-CC154." (PMID 35342351, 2022).
Cirrhosis (1 paper, 2017). A chronic disorder of the liver in which liver tissue becomes scarred and is partially replaced by regenerative nodules and fibrotic tissue resulting in loss of liver function. "However, none of MTNR1B SNPs examined was found to be individually associated with clinical stage, tumor size, lymph node metastasis, distant metastasis, vascular invasion, Child-Pugh classification, prevalence of hepatitis B virus (HBV) and hepatitis C virus (HCV) infections, and cirrhosis." (PMID 29156748, 2017).
colorectal cancer (1 paper, 2023). A primary or metastatic malignant neoplasm that affects the colon or rectum. "In addition, specific single nucleotide polymorphism (SNP) variants in MTNR1B combined with CDKN2A and MGMT genes hypermethylation were found to cause worse 5-year overall survival in colorectal cancer patients, suggesting significant role of SNP variants of MTNR1B in cancer pathogenesis." (PMID 37371885, 2023).
glioblastoma (1 paper, 2026). The most malignant astrocytic tumor (WHO grade IV). "In this study, transcriptomic data from TCGA, CGGA, and GTEx were integrated to characterize the expression patterns of melatonin receptors (MTNR1A and MTNR1B) and biosynthetic enzymes (AANAT and ASMT) across normal brain tissue, lower-grade glioma and glioblastoma." (PMID 42286740, 2026).
Graves disease (1 paper, 2020). Graves' disease is an autoimmune disorder that leads to overactivity of the thyroid gland (hyperthyroidism).It is caused by an abnormal immune system response that causes the thyroid gland to produce too much thyroid hormones. "Melatonin receptors MTNR1A and MTNR1B SNPs have been linked to autoimmune diseases, including Graves' disease in a study on 83 Hashimoto's thyroiditis showing variations of rs2119882 of MTNR1A supporting melatonin pathway involvement in Graves' disease pathogenesis." (PMID 32685724, 2020).
Hashimoto thyroiditis (1 paper, 2025). An autoimmune disorder caused by the production of autoantibodies against thyroid tissue. "This study is the first one aimed at examining the association between MTNR1B polymorphisms and BMI in patients with Hashimoto’s thyroiditis." (PMID 40332199, 2025).
hepatocellular carcinoma (1 paper, 2021). A malignant tumor that arises from hepatocytes. "In a large Taiwan study, five MTNR1A SNPs (rs13140012, rs6553010, rs2119882, rs13113549, and rs2375801) as well as five MTNR1B SNPs (rs1387153, rs1562444, rs4611171, rs10765576, and rs10830963) were evaluated in patients with hepatocellular carcinoma cancer (HCC)." (PMID 35008896, 2021).
liver cancer (1 paper, 2017). An epithelial or non-epithelial malignant neoplasm that arises from the liver. "While adjusted for age and alcohol use, we found that a specific haplotype of MTNR1B (GCGT) was significantly associated with increased susceptibility to HCC (AOR, 2.132; 95% CI, 1.106–4.111; p = 0.024), further suggesting a genetic predisposition of MTNR1B to liver cancer." (PMID 29156748, 2017). "Here, we performed a hypothesis-driven case-control study to evaluate the impact of gene variations of MTNR1A and MTNR1B on the risk and progression of HCC and observed an association of melatonin receptor gene polymorphisms with the risk of HCC, liver cancer metastasis, and augmented liver damage." (PMID 29156748, 2017).
lung carcinoma (1 paper, 2019). "MTNR1B mRNA expression levels in selected lung cancer cell lines were statistically insignificant." (PMID 31319607, 2019).
maturity-onset diabetes of the young (1 paper, 2011). "Furthermore, a study with European populations also found significant associations between variations of MTNR1B with BMI and FPG, but not with maturity-onset diabetes of the young (MODY) or T2DM." (PMID 21658282, 2011).
myocardial infarction (1 paper, 2023). Gross necrosis of the myocardium, as a result of interruption of the blood supply to the area, as in coronary thrombosis. "In this case-control study, we studied the association between melatonin receptor 1B gene polymorphisms and susceptibility to myocardial infarction in surviving patients." (PMID 37511203, 2023). "We aimed to investigate the association of MTNR1B polymorphisms with chronotype and susceptibility to myocardial infarction." (PMID 37511203, 2023). "Rather, they may indicate that MTNR1B polymorphisms are a minor risk factor for myocardial infarction." (PMID 37511203, 2023). "Therefore, the aim of the present study was to investigate a possible association of MTNR1B polymorphisms with chronotype and susceptibility to myocardial infarction." (PMID 37511203, 2023). "Rather, they may indicate that the MTNR1B gene polymorphisms are minor risk factors for susceptibility to myocardial infarction." (PMID 37511203, 2023). "As some previous studies have shown, the present negative results do not exclude the role of the MTNR1B polymorphisms studied in the development of myocardial infarction." (PMID 37511203, 2023). "The present case-control study included 199 patients with myocardial infarction (MI) (57% men) and 198 control participants (52% men) without previous cardiovascular diseases who underwent genotyping for the MTNR1B polymorphisms rs10830963, rs1387153, and rs4753426 from peripheral blood samples." (PMID 37511203, 2023).
osteosarcoma (1 paper, 2021). A usually aggressive malignant bone-forming mesenchymal neoplasm, predominantly affecting adolescents and young adults. "We developed a four-immune gene prognostic index of osteosarcoma, including CD79A, CSF3R, MTNR1B and NPPC." (PMID 33371790, 2021).
Parkinson disease (1 paper, 2013). A progressive degenerative disorder of the central nervous system characterized by loss of dopamine producing neurons in the substantia nigra and the presence of Lewy bodies in the substantia nigra and locus coeruleus. "The other markers (i.e., CAPN6, COL1A2, COL3A1, GALA1 and MTNR1B) belong to gene families with a known role in other neurodegenerative diseases, such as Alzheimer’s or Parkinson’s disease in humans." (PMID 23497022, 2013).
prion disease (1 paper, 2013). A transmissible disease that is caused by a protein that is able to induce abnormal folding of normal cellular proteins, leading to characteristic spongiform brain changes, which are associated with neuronal loss without an inflammatory response. "In conclusion, this study of gene transcription and protein expression and distribution confirm CAPN6, GALA1, MTNR1B and MT2A as potential targets for further prion disease research." (PMID 23497022, 2013).
scoliosis (1 paper, 2025). A congenital or acquired spinal deformity characterized by lateral curvature of the spine. "Tryptophan hydroxylase (TPH1 rs10488682), insulin-like growth factor (IGF1 rs5742612), neurotrophin 3 (NTF3 gene promoter at rs11063714), interleukin-17 receptor C (IL17RC rs708567), melatonin receptor 1B (MTNR1B rs4753426) were identified as risk factors for scoliosis curve progression." (PMID 39781499, 2025).
uveal melanoma (1 paper, 2024). A melanoma derived from melanocytes of the uveal tract. "In the study, receptor agonists for both MTNR1A and MTNR1B as well as melatonin itself inhibited the growth of uveal melanoma cells at physiological concentrations, thereby suggesting a receptor-mediated mechanism for the inhibition of tumor cell growth." (PMID 39201396, 2024). "As previously stated, an earlier study found that MTNR1A and MTNR1B agonists as well as melatonin had a beneficial effect on uveal melanoma cells." (PMID 39201396, 2024). "As mentioned, one previous study has found the expression of MTNR1B in a uveal melanoma cell line." (PMID 39201396, 2024). "We examined the expression of melatonin receptors in uveal melanoma tumors from two separate cohorts and identified the presence of four receptors including the two main melatonin receptors MTNR1A and MTNR1B as well as RORα and NQO2." (PMID 39201396, 2024).
cancer (9 papers, 2015 to 2025). A tumor composed of atypical neoplastic, often pleomorphic cells that invade other tissues. "While PD1 GG appears to have a protective function, the role of MTNR1B polymorphisms requires further investigation to understand its precise impact on cancer risk." (PMID 40736027, 2025). "The PD1 and MTNR1B gene polymorphisms have been extensively studied for their potential role in cancer susceptibility." (PMID 40736027, 2025). "Increased expressions of MTNR1A and MTNR1B have been shown to promote the inhibitory actions of melatonin on the growth of cancer cells." (PMID 29163852, 2017). "Mounting evidence indicates that melatonin exhibits oncostatic properties in many cancer types mainly mediated by its membrane-bound receptors, melatonin receptor 1A (encoded by MTNR1A) and 1B (MTNR1B)." (PMID 29163852, 2017). "Increasing evidence indicates that melatonin exhibits oncostatic properties in many cancer types at least in part mediated by its membrane-bound receptors, melatonin receptor 1A (encoded by MTNR1A) and 1B (MTNR1B)." (PMID 29156748, 2017). "MTNR1A is vastly more abundant than MTNR1B, and there is evidence that melatonin’s growth-inhibitory effects on several cancer cells are MTNR1A receptor-dependent." (PMID 25806809, 2015). "Moreover, MTNR1B, which was rarely differentially expressed in pan-cancer transcriptional analysis, was significantly differentially hypermethylated in five cancer types, whereas frequent differentially underexpressed RORA did not exhibit consistent hypermethylation." (PMID 33842355, 2021). "Whereas there are nine rhythm genes (MTNR1B, NR1D1, RORB, RORA, OPN4, C1orf51, PROK2, SERPINE, and EGR3) that are differently expressed in the high and low MSI group in more than 1/3 cancer types." (PMID 31927791, 2020). "Among them, six melatonergic genes were significant unfavorable factors in cancers (e.g., MTNR1A in ESCA and LIHC; GPR50 in KIRC, LIHC, and STAD; NQO2 in BRCA, LIHC, and LUSC; CYP1B1 in KIRC and STAD; ASMT in ESCA, HNSC, and LUAD; and MTNR1B in STAD)." (PMID 33842355, 2021).
tumor (8 papers, 2017 to 2026). "Expression of AANAT, ASMT, MTNR1A and MTNR1B progressively declined with increasing tumour grade and was associated with poor prognosis." (PMID 42286740, 2026). "Erik cohort of 47 patients, expression levels were analyzed in the nuclei and cytoplasm of 45 tumor samples as the slides immunohistochemically stained for MTNR1B were missing for two patients." (PMID 39201396, 2024). "It was shown that CART was expressed only in the tumor (in 4/10 of cases), while MTNR1b and rGLP1 were expressed in the tumor (in 6/10 and 10/10, respectively) and the islets of Langerhans (in 5/9 and 9/9, respectively)." (PMID 39868444, 2024). "In the current study, mRNA expression for MTNR1a and MTNR1b genes was detected in the tumor microenvironment." (PMID 32499868, 2020). "In mammals, MT typically regulates survival signaling and tumor progression through two G protein-coupled membrane receptors, namely MT receptor 1 A (MTNR1A) and MT receptor 1B (MTNR1B)." (PMID 41145438, 2025). "Moreover, while MT typically regulates survival signaling and tumor progression through its G protein-coupled membrane receptors, MTNR1A and MTNR1B, our findings suggest a receptor-specific effect." (PMID 41145438, 2025).
metabolic disorders (7 papers, 2019 to 2025). "Notable, MTNR1B gene showed a more prominent association with clusters related to metabolic diseases, including glucose metabolism, compared to related genes such as MTNR1A or RORA." (PMID 40697662, 2025). "For example, variants in several clock genes (including BMAL1 and PER2) as well as in the melatonin receptor 1B (MTNR1B) gene are associated with an increased risk of specific metabolic disorders." (PMID 35324893, 2022). "T2DM is a multi-gene metabolic disease and in this study we found that the MTNR1B gene variant has a certain effect on the efficacy of nateglinide." (PMID 34118937, 2021).
retinopathy (1 paper, 2013). "Moreover, for any retinopathy, there were several nominally significant associations with SNPs close to the ANK1, SLC30A8, MTNR1B, TMPRSS6 and HK1 loci." (PMID 24244560, 2013).
MTNR1B also shares sentences with these, for which no sentence is quoted: cardiovascular disease (2 papers); neurodegenerative disease (2); pancreatic cancer (2); polycystic ovary syndrome (2); type 1 diabetes (2); acne (1); Alzheimer’s dementia (1); cervical cancer (1); clear cell renal cell carcinoma (1); endometrial cancer (1); esophageal cancer (1); glioma (1); hair diseases (1); Horseshoe kidney (1); hypertriglyceridemia (1); inflammatory bowel disease (1); insulinoma (1); leukopenia (1); lymph node metastasis (1); MODY (1); mood disorder (1); multiple sclerosis (1); neuropathy (1); non-small cell lung carcinoma (1); preeclampsia (1); pregnancy hypertension (1); rheumatoid arthritis (1); systemic lupus erythematosus (1).